USP9X (ubiquitin specific peptidase 9 X-linked)
Diseases named in the same sentence as USP9X in open-access papers (continued):
Sharing a sentence is not in itself a finding about the gene and the disease.
glioma (6 papers, 2016 to 2025). A benign or malignant brain and spinal cord tumor that arises from glial cells (astrocytes, oligodendrocytes, ependymal cells). "USP9X stabilizes and deubiquitinates β-catenin by removing the Lys 48-linked polyubiquitin chains that mark it for proteasomal degradation, thereby promoting glioma cell proliferation and survival and indicating it as a therapeutic target in high-grade gliomas." (PMID 33158118, 2020). "HDAC6 and USP9X protein levels were increased in glioma and GBM tissues compared to normal tissues in publicly available databases, including Human Protein Atlas." (PMID 40162736, 2025). "Mutations in XIE genes USP9X, NLGN4x, PLXNB3 (involved in axonal guidance and glioma invasion), SYAP1, SRPX2, and ZFX (ZFX-SMARCA1 fusion) occurred in non-MN1-BEND2, predominantly female cases." (PMID 35440587, 2022). "To determine the role of USP9X in modulating glioma tumorigenesis in vivo, we implanted primary glioma cells and lentivirus infected primary glioma cells into the dorsal side of the left hind legs of mice." (PMID 27783990, 2016). "The expression of USP9X and β-catenin was significantly correlated (Spearman's rank test, P <0.001) in high grade glioma tissues." (PMID 27783990, 2016). "The expression of USP9X was also significantly correlated with the expression of c-Myc and cyclinD1 in high grade glioma tissues (Spearman's rank test, P <0.001)." (PMID 27783990, 2016). "Increased USP9X expression correlates with increased β-catenin protein in high grade glioma tissues." (PMID 27783990, 2016). "So, knockdown of USP9X not only inhibited the proliferation of glioma cells in vitro, but also suppressed the tumorigenicity of primary glioma cells in vivo." (PMID 27783990, 2016). "In summary, these results indicate that USP9X stabilizes β-catenin and activates Wnt/β-catenin signal pathway to promote glioma cell proliferation and survival." (PMID 27783990, 2016). "The clinical materials of 54 high grade glioma patients were collected and tumor tissues from these patients were immunohistochemically assessed to detect USP9X expression." (PMID 27783990, 2016). "The USP9X-shRNA group formed much smaller tumors and displayed reduced tumorigenicity, showing that downregulation of USP9Xreduced primary glioma cell tumorigenesis in vivo." (PMID 27783990, 2016). "Down-regulation of USP9X also consistently inhibits the tumorigenicity of primary glioma cells in vivo." (PMID 27783990, 2016). "Using immunohistochemistry, we found that USP9X positive reactions primarily occurred in the cytoplasm of high grade glioma cells and produced brownish yellow granules." (PMID 27783990, 2016). "Here we show that the deubiquitinase USP9X stabilizes β-catenin and thereby promotes high grade glioma cell growth." (PMID 27783990, 2016). "To further explore the molecular mechanisms of USP9X in high grade gliomas, we studied the key molecular pathways involved in action." (PMID 27783990, 2016). "As inhibition of USP9X resulted in caspase 3 and caspase 8 activation and increased the rates of apoptosis, USP9X might promote cell survival by inhibiting apoptosis in glioma cells." (PMID 27783990, 2016). "Among 54 glioma cases, there were 26 USP9X positive cases, representing a positive rate of 48.1%." (PMID 27783990, 2016). "Our findings may provide new evidence that regulation of USP9X could potentially be a plausible method for improvement of prognosis in high grade glioma patients." (PMID 27783990, 2016). "We also detected whether USP9X affected the apoptosis of glioma cells." (PMID 27783990, 2016). "USP9X could also potentially be a therapeutic target in high grade gliomas." (PMID 27783990, 2016). "Moreover, patients with high grade glioma overexpressing USP9X have a poor prognosis." (PMID 27783990, 2016). "Here, we hypothesize that USP9X interacts with and stabilizes β-catenin in glioma cells." (PMID 27783990, 2016). "Subsequently, we detected whether USP9X affected the cell cycle of glioma cells." (PMID 27783990, 2016).
glioma (continued). "Thus, it appears that targeting Usp9X might have impact on glioma growth and could be preferentially targeted over normal non-neoplastic tissue." (PMID 26872380, 2016). "USP9X could also potentially be a novel therapeutic target for high grade gliomas." (PMID 27783990, 2016). "Our observations suggest that L-asparaginase sensitizes glioma cells to ABT263 in part by modulation of Noxa, Mcl-1 and Usp9X levels." (PMID 27172899, 2016).
brain tumor (5 papers, 2013 to 2016). "USP9X has also been reported to increase the levels of β-catenin, a transcription factor linked to the growth of brain tumors, and overexpression of USP9X has been reported to enhance the half-life and expression of β-catenin in mouse L cells and MCF7 cells, respectively." (PMID 23667531, 2013). "Not surprisingly, knockdown of the RNA binding protein Musashi 2 or the deubiquitinating enzyme USP9X, which have been shown to associate with SOX2 in multiple cell types, disrupts the self-renewal of ES cells and inhibits the growth of brain tumor cells." (PMID 27145457, 2016). "Although the critical roles of USP9X in brain tumor cells remain to be determined, USP9X is most likely involved in the removal of ubiquitin from its target proteins." (PMID 23667531, 2013). "Another recent report supports the relevance of Usp9X in brain tumors." (PMID 26872380, 2016). "Concerning Usp9X, the present literature suggests that while Usp9X has a pivotal role during the development of the nervous system, its expression declines in the mature brain, suggesting that it is a specific therapeutic target for primary brain tumors." (PMID 26008975, 2015). "Recent studies have implicated MSI2, a putative RNA binding protein, and USP9X, a deubiquitinating enzyme, in several cancers, but not brain tumors." (PMID 23667531, 2013). "Thus, future efforts will be needed to determine how knockdown of USP9X influences the fate of brain tumor cells." (PMID 23667531, 2013). "Therefore, we expanded our analysis of SOX2-associated proteins by determining whether decreasing MSI2 and USP9X expression influences the behavior of brain tumor cells." (PMID 23667531, 2013). "Furthermore, MSI2 and USP9X have been implicated in other cancers, but their roles in brain tumors have not been examined." (PMID 23667531, 2013). "We also demonstrate that the knockdown of USP9X in DAOY, U87 and U118 brain tumor cells strongly reduces their growth." (PMID 23667531, 2013).
developmental delay (5 papers, 2015 to 2025). "Females with heterozygous pathogenic USP9X variants can be asymptomatic, but can also have developmental delay, structural brain malformations, dysmorphisms, short stature, choanal atresia, postaxial polydactyly, congenital heart disease, facial clefting, anal atresia, and scoliosis." (PMID 36653407, 2023).
metastatic disease (5 papers, 2016 to 2025). "In this report, PDA patients with low USP9x levels showed poor survival and were more likely to have metastatic disease compared with other patients." (PMID 27462448, 2016). "Hopefully, targeting PD‐L1 by blocking USP9X might be a potentially useful strategy to treat OSCC, especially metastatic tumors." (PMID 29992764, 2018).
Alzheimer disease (4 papers, 2015 to 2025). A progressive, neurodegenerative disease characterized by loss of function and death of nerve cells in several areas of the brain leading to loss of cognitive function such as memory and language. "This study investigates the link between ubiquitin‐specific peptidase 9 X‐linked (USP9X) and Alzheimer's disease (AD) pathogenesis, aiming to identify potential targets for AD diagnosis, treatment, and drug development." (PMID 40586131, 2025). "Results from experimental animal models have implicated USP9X in neurodegeneration, including Parkinson’s and Alzheimer’s disease, as well as autoimmune diseases." (PMID 25672900, 2015). "Among the genes that were significantly altered in the public post‐mortem brain tissues of Alzheimer's disease (AD) patients, USP9X was included, and it showed a very significant gender expression difference in ad." (PMID 40586131, 2025). "A role for USP9X in the degradation of accumulated proteins has also been suggested in Huntington’s and Alzheimer’s disease." (PMID 25672900, 2015). "Therefore, targeting Raptor and USP9X holds promise as a therapeutic strategy for Alzheimer’s disease." (PMID 39449082, 2024). "Targeting the USP9X-Raptor-mTORC1 axis may provide a novel strategy for promoting autophagy and mitigating tau pathology in Alzheimer’s disease and other tauopathies." (PMID 39449082, 2024). "Likewise, the only protein involved in the ubiquitin system that was significantly changed was FAF-X (USP9X) which has been implicated in both Parkinson's- and Alzheimer's-disease." (PMID 34401662, 2021).
atherosclerosis (4 papers, 2022 to 2025). A disease characterized by the build-up of fatty material and calcium deposition in the arterial wall resulting in partial or complete occlusion of the arterial lumen. "We found that USP9X regulated foam cell formation and was negatively associated with atherosclerosis in rodents and humans." (PMID 35389885, 2022). "Although the regulation of USP9X by noncoding RNAs in the context of atherosclerosis is still unknown, the current evidence suggests that it is worth investigating the underlying mechanism with a view to developing a therapeutic USP9X agonist for atherosclerosis." (PMID 35389885, 2022). "However, our findings raise the possibility that USP9X inhibitors may cause side effects in the cardiovascular system by inducing atherosclerosis progression." (PMID 35389885, 2022). "As expected, the administration of an inhibitory peptide against USP9X for 10 weeks promoted foam cell formation and atherosclerosis in ApoEKO mice." (PMID 36834633, 2023). "K63 polyubiquitination on SR-A1 stimulated oxidized LDL uptake and proinflammatory cytokine expression in macrophages, suggesting the protective roles of macrophage USP9X for atherosclerosis." (PMID 36834633, 2023). "In this study, we identified macrophage USP9X as a beneficial regulator of atherosclerosis and revealed the specific mechanisms for the development of potential therapeutic strategies for atherosclerosis." (PMID 35389885, 2022). "Based on this result, we synthesized the corresponding cell-penetrating inhibitory peptide (peptide-I) and studied the effects of blocking the combination of SR-A1 and USP9X on foam cell formation and atherosclerosis in vitro and in vivo." (PMID 35389885, 2022). "In summary, our current study demonstrated that USP9X has a role in inhibiting the development of atherosclerosis." (PMID 35389885, 2022). "We found that USP9X expression in lesional macrophages was reduced during atherosclerosis development in both humans and rodents." (PMID 35389885, 2022). "However, recent investigation led by Wang and colleagues discovered that USP9X executed protective function in the development of atherosclerosis." (PMID 40963913, 2025). "Therefore, the retention of USP9X on SR-A1 in macrophages is likely to be a promising therapeutic strategy for atherosclerosis treatment." (PMID 36834633, 2023). "USP9X, 14, 17, and 20 in vascular cells are postulated to be determinants of atherosclerosis." (PMID 36834633, 2023). "Therefore, our research defined the functional role of macrophage USP9X in atherosclerosis and highlights potentially new strategies for treating this disease." (PMID 35389885, 2022). "Moreover, blocking binding of USP9X to SR-A1 with a cell-penetrating peptide exacerbated foam cell formation and atherosclerosis." (PMID 35389885, 2022). "Blockade of the USP9X–SR-A1 interaction promotes foam cell formation and atherosclerosis." (PMID 35389885, 2022). "Furthermore, disrupting the interaction between SR‐A1 and USP9X with a cell‐penetrating peptide exacerbates atherosclerosis by increasing foam cell formation, showing that USP9X is an important beneficial regulator of atherosclerosis." (PMID 38778460, 2024).
bladder cancer (4 papers, 2015 to 2021). "In addition, BIX-01294 induced less apoptosis in Control siRNA knockdown bladder cancer cells than that in USP9X siRNA knockdown cells." (PMID 25685062, 2015). "In summary, our data demonstrate that BIX-01294 induces ER stress pathway, resulting in up-regulation of PMAIP1 and down-regulation of USP9X and MCL1, leading to apoptosis in bladder cancer cells." (PMID 25685062, 2015). "Taken together, BIX-01294 decreases the expression of USP9X and promotes the degradation of MCL1, which eventually leads to apoptosis in bladder cancer cells." (PMID 25685062, 2015). "Although we genetically silenced USP24 to prove the stabilization of GSDMB by USP24, we could not rule out that USP9x or USP5 acted as deubiquitinases of GSDMB in bladder cancer." (PMID 34326684, 2021).
cholangiocarcinoma (4 papers, 2021 to 2025). A carcinoma that arises from the intrahepatic biliary tree (intrahepatic cholangiocarcinoma) or from the junction, or adjacent to the junction, of the right and left hepatic ducts (hilar cholangiocarcinoma). "EGLN3 is associated with various tumor conditions, and USP9X relieves cholangiocarcinoma by upregulating EGLN3." (PMID 37842058, 2023). "In conclusion, our results unveil USP9X as a potential diagnostic, prognostic and therapeutic tool for cholangiocarcinoma, which provides a novel approach for use in noninvasive screening of cholangiocarcinoma." (PMID 34112167, 2021). "The underlying molecular mechanism of USP9X in cholangiocarcinoma was determined by immunoblotting, co-immunoprecipitation and quantitative real time PCR (qPCR)." (PMID 34112167, 2021). "The results demonstrated that high expression levels of USP9X are associated with better prognosis of patients with cholangiocarcinoma in OS." (PMID 34112167, 2021). "Consequently, we provide novel insight into that USP9X is a potential biomarker or serves as a therapeutic or diagnostic target for cholangiocarcinoma." (PMID 34112167, 2021). "For instance, in pancreatic ductal adenocarcinoma (PDAC), colorectal cancer, and cholangiocarcinoma, USP9X inhibits tumor progression by modulating specific signaling pathways." (PMID 41301681, 2025). "The purpose of this study was to investigate the function and mechanism of USP9X in cholangiocarcinoma." (PMID 34112167, 2021). "IHC analysis for 54 cases of cholangiocarcinoma tissues and 12 cases of para-tumor tissues also showed that positive staining of the USP9X protein was enriched in para-tumor tissues, but was rarely observed in cholangiocarcinoma tissues." (PMID 34112167, 2021). "The expression of USP9X in cholangiocarcinoma inhibited cell proliferation and colony formation in vitro as well as xenograft tumorigenicity in vivo." (PMID 34112167, 2021). "The results suggested that compared with cholangiocarcinoma tissues, USP9X expression level was significantly higher in para-tumor tissues." (PMID 34112167, 2021). "More importantly, the clinical significance and the biological roles of USP9X in cholangiocarcinoma remain unexplored." (PMID 34112167, 2021). "A novel pathway through which USP9X / EGLN3 provides promising diagnostic and therapeutic targets against cholangiocarcinoma." (PMID 34112167, 2021). "USP9X positively regulated the expression level of apoptosis pathway genes de through EGLN3 thus involved in apoptosis of cholangiocarcinoma." (PMID 34112167, 2021). "In this study, USP9X modulates the malignant potential of cholangiocarcinoma through regulation of EGLN3." (PMID 34112167, 2021). "Here we demonstrated that USP9X is downregulated in cholangiocarcinoma which contributes to tumorigenesis." (PMID 34112167, 2021). "To validate this finding, we investigated the effect of USP9X expression on postoperative survival in cholangiocarcinoma patients by immunohistochemistry (IHC)." (PMID 34112167, 2021). "In summary, this study is the first to demonstrate that USP9X exerts tumor-suppressive effects in cholangiocarcinoma by deubiquitinating and stabilizing the EGLN3 protein, thereby activating the KIF1Bβ-mediated apoptotic pathway and establishing a novel USP9X-EGLN3-KIF1Bβ tumor-suppressive axis." (PMID 41301681, 2025). "Notably, in cholangiocarcinoma, USP9X promotes apoptosis by deubiquitinating EGLN3 and regulating the expression of KIF1Bβ, highlighting its crucial role in tumor suppression." (PMID 41301681, 2025). "Therefore, USP9X exerts its tumor inhibitory effect through EGLN3 thus regulated apoptosis pathway by KIF1Bβ in cholangiocarcinoma." (PMID 34112167, 2021). "Therefore, USP9X promotes the apoptosis of cholangiocarcinoma cells and alleviates malignant progression of tumor cells." (PMID 34112167, 2021). "On the basis of these analyses, we next examined whether EGLN3 expression correlates with USP9X in cholangiocarcinoma cells." (PMID 34112167, 2021).
cholangiocarcinoma (continued). "Findings presented here show that USP9X plays a suppressive role in cholangiocarcinoma progression." (PMID 34112167, 2021). "USP9X functions as a tumor suppressor to participate in apoptosis activation of cholangiocarcinoma." (PMID 34112167, 2021). "Although the role of USP9X in tumor varies according to tumor type and stage, in our report, we described its inhibitory effect in cholangiocarcinoma, which provides a new therapeutic target and predictor for cholangiocarcinoma." (PMID 34112167, 2021). "Consequently, evaluating the therapeutic potential of USP9X in cholangiocarcinoma deserve large-scale studies." (PMID 34112167, 2021). "Furthermore, IHC staining of 54 cases of cholangiocarcinoma tissue suggested that the expression of Ki-67 was markedly downregulated in USP9X high samples but upregulated in USP9X low samples, which demonstrated that the expression level of USP9X was negatively correlated with Ki67 expression." (PMID 34112167, 2021). "This review synthesizes current knowledge on six USP members—USP1, USP3, USP8, USP9X, USP21, and USP22—and delineates their context-dependent roles across cholangiocarcinoma and GBC subtypes." (PMID 41301681, 2025). "Immunoblotting and immunohistochemistry were used to assess the expression profiling of USP9X and EGLN3 in cholangiocarcinoma patients." (PMID 34112167, 2021). "The protein level of USP9X in cholangiocarcinoma tissues was lower than adjacent noncancerous tissues." (PMID 34112167, 2021). "In cholangiocarcinoma (CCA), the tumor suppressor KIF1Bβ induced apoptosis and was up-regulated by Egl nine homolog 3 (EGLN3), and ubiquitin-specific peptidase 9X (USP9X) acted to de-ubiquitinate and stabilize EGLN3 thereby accelerating this process." (PMID 38433242, 2024). "Furthermore, we evaluated the expression level of USP9X in a cohort of 6 pairs of cholangiocarcinoma and para-tumor (non-cancerous) tissues by immunoblotting." (PMID 34112167, 2021). "To further identify the clinical relevance of our findings, we evaluated the correlation of expression levels between USP9X and EGLN3 in 5 pairs of primary cholangiocarcinoma and matched adjacent noncancerous tissues by immunoblotting." (PMID 34112167, 2021).
chronic myelogenous leukemia (4 papers, 2011 to 2022). "For instance, the USP9X inhibitor WP1130 lowers Mcl-1 levels in chronic myelogenous leukemia and enhances sensitivity to apoptosis by facilitating Mcl-1 degradation." (PMID 35301297, 2022). "The USP9X inhibitor WP1130 lowers MCL-1 levels in chronic myelogenous leukemia and enhances sensitivity to apoptosis by facilitating MCL-1 degradation." (PMID 28659182, 2017). "The reduced USP9X and MCL1 levels were recently found to block BCR-ABL kinase signaling, taking chronic myelogenous leukemia cells to apoptosis." (PMID 22016818, 2011).